TSLP (thymic stromal lymphopoietin)
Diseases named in the same sentence as TSLP in open-access papers (continued):
Sharing a sentence is not in itself a finding about the gene and the disease.
breast carcinoma (42 papers, 2012 to 2025). "TSLP-induced breast cancer suppression was associated with CD4+ T cell accumulation around breast cancer." (PMID 40873585, 2025). "Recently, TSLP has been linked to the pathogenesis of different tumors, like breast cancer, acute lymphocytic leukemia (ALL), cutaneous T cell lymphomas, and enhanced lung metastasis." (PMID 38557942, 2024). "TGF-β3 and TSLP were reported to be expressed in breast cancer and associated with both pro- and antitumor activities." (PMID 38236642, 2024). "TSLP loss in breast cancers compared with normal glands was validated across a large collection of breast tissue samples represented in the Cancer Genome Atlas (TCGA) and the Genotype-Tissue Expression (GTEx) databases." (PMID 35657353, 2022). "In those risk predictors, the level of TSLP expression was correlated with breast cancer growth and metastasis." (PMID 36092942, 2022). "TSLP is a cytokine that promotes Th2-mediated immune activity and is associated with a poor prognosis in breast cancer and other epithelial cancers." (PMID 36467500, 2022). "TSLP gene knock down or TSLPR deficiency decreased breast cancer cell growth and metastasis, indicating a critical role of TSLP in cancer metastasis." (PMID 34573368, 2021). "In our previous study, we have reported that TSLP/TSLP receptors polymorphism were associated in breast cancer progression in Saudi population." (PMID 34573368, 2021). "We performed a control case study to examine the correlation of expression and polymorphisms of three nucleotides in TSLP with breast cancer (BC) risk in Saudi Arabian females." (PMID 31210014, 2019). "Increased TSLP was detected in some tumors such as breast cancer and pancreatic cancer, both of which are associated with Th2-related chronic inflammation." (PMID 26919238, 2016). "Thus, calcipotriol exhibits a robust antitumor effect in late-stage breast cancer associated with TSLP induction and CD4+ T cell infiltration into the tumors." (PMID 39782693, 2025). "Finally, TSLP is overexpressed by immunohistochemistry in breast cancer compared to normal breast tissue and is associated with an increased risk in breast cancer in Saudi women." (PMID 40873585, 2025). "Finally, we show that high TSLP expression in the human breast cancer is associated with improved survival." (PMID 35657353, 2022). "The loss of TSLP expression was noted across all breast cancer subtypes represented in TCGA." (PMID 35657353, 2022). "Finally, we show the loss of TSLP during human breast cancer development and demonstrate significantly improved survival in patients with high TSLP expression in their breast cancer." (PMID 35657353, 2022). "In addition, TSLP has been implicated in breast cancer pathogenesis by regulating the DC expression of OX40L, differentiating the Th2 cells, and increasing production of IL13." (PMID 34571811, 2021). "TSLP, an IL-7-like inflammatory cytokine, is often associated with the induction of Th2-type allergic responses, which is expressed in cancers including human carcinomas such as breast cancer and melanoma." (PMID 31885639, 2019). "To elucidate the effect of TSLP/Th2 cell induction by calcipotriol on late-stage breast cancer progression, we used a PyMt cell line and established an orthotopic PyMt breast tumor model." (PMID 39782693, 2025). "The same group also examined the possible role of TSLP induction during breast cancer development using the PyMt cell line model in Tslptg mice." (PMID 40873585, 2025). "The authors concluded that TNF-α and IFN-γ produced by TSLP-stimulated CD4+ T cells play a major role in providing antitumor immunity against experimental breast cancer." (PMID 40873585, 2025). "Human breast cancer is heavily infiltrated by Th2 cells driven by OX40L-expressing DCs in response to cancer-derived TSLP." (PMID 40873585, 2025).
breast carcinoma (continued). "Calcipotriol-induced TSLP released from skin keratinocytes primarily leads to the activation of Th2 cells that drive breast cancer cells into terminal differentiation during early-stage tumor development." (PMID 39782693, 2025). "Using mouse and human bone marrow aspirates incubated with metastatic 4T1 breast cancer cells, the authors demonstrated that this was the result of TSLP release from cancer cells." (PMID 40873585, 2025). "In a mouse model of breast cancer, TSLP activated resident macrophages to release VEGF-A, the most potent proangiogenic factor." (PMID 40873585, 2025). "TSLP exhibits diverse roles in various diseases, including contradictory effects in cancers such as breast cancer." (PMID 40787610, 2025). "Studies on breast cancer cell line models have shown that the endogenous TSLP signal is co-opted by cancer cells to promote their growth." (PMID 39782693, 2025). "The authors concluded that a breast-myeloid cell axis, mediated via TSLP and IL-1α, promotes the progression of breast cancer and metastasis formation." (PMID 40873585, 2025). "In a mouse model, TSLP released from breast cancer downregulates the receptors, CXCR4 and α4β1 integrin, which physiologically keep B-cell precursors in bone marrow." (PMID 40873585, 2025). "Collectively, these results demonstrate that CD4+ T cells and TSLP signaling are required for calcipotriol-induced antitumor response against late-stage breast cancer, which is accompanied by a significant accumulation of IL-24+ cells within the TME." (PMID 39782693, 2025). "We have previously demonstrated that TSLP-stimulated CD4+ Th2 cell immunity suppresses early stages of breast cancer development." (PMID 39782693, 2025). "Mouse and human breast cancer cells express TSLP, which promotes Th2 differentiation of CD4+ T cells." (PMID 40873585, 2025). "Some studies suggest that TSLP can promote the growth and metastasis of breast cancer, indicating a pro-tumorigenic role." (PMID 40787610, 2025). "Contrastingly, other study shows that high expression of TSLP in keratinocytes within mouse models can suppress breast cancer development, suggesting a protective effect." (PMID 40787610, 2025). "Herein, we demonstrate that Th2 cells induced by the topical calcipotriol/thymic stromal lymphopoietin cytokine axis suppressed the growth of established mammary tumors in mice." (PMID 39782693, 2025). "We demonstrated that the induction of TSLP by topical calcipotriol treatment inhibited mammary tumor growth by activating CD4+ T cells." (PMID 39782693, 2025). "In summary, we demonstrate the efficacy of topical calcipotriol in inhibiting mammary tumor growth in a TSLP- and CD4+ T cell–dependent manner." (PMID 39782693, 2025). "Our findings reveal that TSLP-stimulated CD4+ Th2 cells suppress mammary tumor growth by promoting IL-24+ TAM development and IL-24–mediated tumor cell apoptosis." (PMID 39782693, 2025). "On the other hand, another relevant function of TSLP was further explored in a breast cancer model, demonstrating an increase in antiapoptotic molecules, such as Bcl-2 and Bcl-x." (PMID 38557942, 2024). "One study demonstrated that the TSLP pathway contributes to the progression of metastatic breast cancer by promoting a Th2-type tumor microenvironment to blunt anti-tumor immunity." (PMID 38566968, 2024). "In a mouse model of breast cancer, curdlan-activated DCs were reprogrammed and acquired resistance to cancer cell-derived thymic stromal lymphopoietin (TSLP)." (PMID 39590166, 2024). "In contrast, other studies have suggested that TSLP can have tumour‐suppressive activity in breast cancers and cutaneous T‐cell lymphoma." (PMID 37165746, 2023). "Thymic Stromal Lymphopoietin (TSLP)-stimulated CD4+ T cells play a vital role in antitumor immunity in advanced breast cancers." (PMID 36761753, 2023).
breast carcinoma (continued). "Our findings demonstrate that TSLP-stimulated CD4+ T cell immunity can block breast cancer growth by inducing a cellular senescent phenotype in advanced breast tumors." (PMID 36467403, 2022). "In contrast to early breast cancer suppression, the antitumor immunity mediated by TSLP-stimulated CD4+ T cells in advanced breast cancer is mediated by the induction of a senescent-like phenotype in cancer cells." (PMID 36467403, 2022). "Consistent with our findings in mice, TSLP expression by mammary epithelial cells was lost during the early phases of breast cancer promotion." (PMID 35657353, 2022). "Collectively, our research on TSLP induction in breast cancer reveals that during the early stages of breast cancer development, cancer cells respond to TSLP-activated CD4+ T cell immunity by undergoing terminal differentiation." (PMID 36467403, 2022). "TSLP is an interleukin-7 (IL-7)-like cytokine that is involved in the progression of various cancers and is a key mediator of breast cancer progression." (PMID 35472078, 2022). "Our findings provide novel insights into the mechanism of CD4+ T cell immunity and highlight TSLP induction as a potential therapeutic strategy in advanced breast cancer." (PMID 36467403, 2022). "Our findings demonstrate that TSLP-stimulated CD4+ T cell immunity blocks breast cancer promotion by engulfing primary breast tumors and transforming them into low-grade, fibrocystic structures, with no metastatic potential." (PMID 35657353, 2022). "We find that baseline TSLP, which is expressed by mammary epithelial cells and actively lost in breast cancers of mice and humans, has a similar tumor protective effect." (PMID 35657353, 2022). "In this study, we investigated the role of TSLP induction during advanced breast cancer development using the PyMt cell line model in the context of TSLP induction in Tslptg mice." (PMID 36467403, 2022). "Previously, research on the effect of TSLP in breast cancer using breast cancer cell lines showed a protumorigenic function for TSLP expressed in the tumor microenvironment." (PMID 35657353, 2022). "Our findings reveal a novel mechanism of TSLP-activated CD4+ T cell immunity against advanced breast cancer, mediated by cellular senescence as a distinct effector mechanism for cancer immunotherapy." (PMID 36467403, 2022). "Together, these findings indicate that TNF-α and IFN-γ produced by TSLP-stimulated inflammatory Th2 cells play a key role in providing antitumor immunity against advanced breast cancer." (PMID 36467403, 2022). "Using an established MMTV-PyMttg breast cancer cell line, we demonstrate that TSLP-stimulated CD4+ T cells possess an antitumor effect in advanced breast cancer." (PMID 36467403, 2022). "Future studies are warranted to determine the effect of transient TSLP induction on advanced breast cancer." (PMID 36467403, 2022). "Breast cancer-derived thymic stromal lymphopoietin (TSLP) has been identified as an inducer of OX40L on DC infiltrating primary breast cancer." (PMID 35309358, 2022). "Collectively, these findings demonstrate that Th2 polarization is essential for TSLP-induced CD4+ T cell immunity against breast cancer development." (PMID 35657353, 2022). "The efficacy of transient and topical TSLP induction in delivering a lasting tumor-specific immunity in the breast highlights the potential for the use of TSLP inducers such as calcipotriol as safe and accessible agents for breast cancer immunoprevention." (PMID 35657353, 2022). "Terminal differentiation as the mode of immunity imposed by TSLP-stimulated Th2 cells against malignant cells in the breast has major implications for preventing breast cancer progression and recurrence in patients." (PMID 35657353, 2022). "To explore the antitumor effect of TSLP induction in early- versus late-stage breast cancer, we examined breast cancer development using the orthotopic breast tumor transfer model." (PMID 36467403, 2022).
breast carcinoma (continued). "We found that classical Th1 cytokines, interferon-gamma (IFN-γ) and tumor necrosis factor-alpha (TNF-α), mediated the antitumor effect of TSLP-activated CD4+ T cells against advanced breast cancer through the induction of cellular senescence." (PMID 36467403, 2022). "Although TSLP levels are overall reduced in breast cancer, high TSLP expression significantly correlated with increased overall and disease-free survival among breast cancer patients represented in TCGA." (PMID 35657353, 2022). "In breast cancer, TSLP produced by cancer cells activates DC and results in Th2 inflammation, which promotes tumorigenesis; whereas in mouse, TSLP can induce immunosuppressive factors by activating CD4+ T cells that promote Th2-mediated immune responses." (PMID 33652749, 2021). "Following the first reports in pancreatic and breast cancer, several studies also in other tumors found either pro-tumor or anti-tumor activity of TSLP, and through Th2-dependent as well as Th2-independent mechanisms." (PMID 33042121, 2020). "The authors showed that human breast cancer cells directly produce TSLP, and that tumor cell derived-TSLP induces in vitro OX40L expression on DCs." (PMID 33042121, 2020). "Next, the roles of GM-CSF and TSLP in arctigenin-regulated anti-tumor effect in breast cancer cells was investigated." (PMID 32887217, 2020). "In both experimental settings breast cancer cells were exposed to high levels of circulating TSLP, were arrested at an early adenoma-like stage, and were prevented from advancing to late carcinoma and metastases." (PMID 33042121, 2020). "In summary, we uncovered that arctigenin exerted anti-tumor effect through decreasing tumor-derived GM-CSF and TSLP, and targeting the proliferation, invasion and stemness of breast cancer cells." (PMID 32887217, 2020). "Collectively, we conclude that arctigenin inhibits the progression of breast cancer by reducing GM-CSF and TSLP expression." (PMID 32887217, 2020). "Studies from the same group showed that, similarly to pancreatic cancer, IL-1β, which was released by myeloid DCs under the influence of tumor-derived factors (i.e., alarmins), was key for TSLP secretion by breast cancer cells." (PMID 33042121, 2020). "The present study showed that arctigenin reduced the expressions of tumor-derived GM-CSF and TSLP through NF-κB p65 to inhibit breast cancer progression." (PMID 32887217, 2020). "Concomitantly and similarly to human pancreatic cancer, a tumor-promoting role for TSLP was demonstrated in breast cancer." (PMID 33042121, 2020). "The results uncovered that arctigenin attenuated the progression of breast cancer through decreasing tumor-derived GM-CSF and TSLP." (PMID 32887217, 2020). "The function of TSLP in favoring development of primary breast cancer and lung metastasis was subsequently confirmed in the same 4T1 transplantable model where cancer cells were grown in TSLPR KO mice." (PMID 33042121, 2020). "In order to determine the impact of systemic TSLP on the early stages of breast cancer development, the authors used two murine models." (PMID 33042121, 2020). "Arctigenin not only inhibited the proliferation, but also the invasion and stemness of breast cancer cells via decreasing GM-CSF and TSLP." (PMID 32887217, 2020). "For example, breast cancer cells have been shown to recruit tumor-infiltrating myeloid cells via the cytokines interleukin (IL)-1α and t thymic stromal lymphopoietin (TSLP) to maintain their survival." (PMID 31416487, 2019). "In recent years, a large number of studies have shown that TSLP is highly expressed in a variety of tumors, including liver cancer, breast cancer, melanoma, etc., and is negatively correlated with the survival time of patients." (PMID 31885639, 2019). "A pro-tumorigenic role of TSLP is supported by a study using an orthotopic model of breast cancer in the mouse." (PMID 30057581, 2018).
breast carcinoma (continued). "This seemed in contrast to the tumor-promoting effect of TSLP reported in pancreatic cancer and breast cancer." (PMID 26919238, 2016). "OX40L fusion protein significantly inhibited the growth of mouse 4T1 breast tumor model and breast cancer cell-derived thymic stromal lymphopoietin (TSLP) contributes to breast tumor development by inducing OX40L expression on DCs." (PMID 22870213, 2012). "As highlighted in breast cancer, thymic stromal lymphopoietin (TSLP) plays a significant role in the tumor microenvironment, influencing the expansion of CD14+CD16+ monocytes, a subset of immune cells that are involved in inflammation and tissue repair, and modulating cellular metabolism." (PMID 40282539, 2025). "TSLP released from breast cancer cells promoted lung metastasis." (PMID 40873585, 2025). "IL-1β selectively induced TSLP secretion from breast cancer cells." (PMID 40873585, 2025). "TSLP provides critical signals for human and mouse B cell proliferation and also expands bone marrow B cell precursors to support lung metastasis in a breast cancer model." (PMID 40873585, 2025). "Furthermore, we have recently demonstrated that TSLP-activated Th2 cells directly block breast cancer development by terminally differentiating the tumor cells to form gland-like structures." (PMID 39744942, 2025). "We investigated whether the ability of calcipotriol to suppress PyMt mammary tumor growth relied on TSLP and CD4+ T cells." (PMID 39782693, 2025). "Our findings demonstrate a role for TSLP induction in the treatment of advanced breast cancer." (PMID 36467403, 2022). "However, it is essential to examine the impact of TSLP/Th2 cell axis in metastatic breast cancer models to fully capture its therapeutic potential." (PMID 35657353, 2022). "TSLP was expressed in the normal breast gland and was lost during early breast cancer development." (PMID 35657353, 2022). "Consistent with a protective role for baseline TSLP expression by mammary epithelial cells against early phases of breast cancer development, we found a significant reduction in TSLP protein levels in terminal PyMttg breast tumors compared with WT mammary glands (P < 0.0001)." (PMID 35657353, 2022). "TSLP at distant sites of breast cancer leads to robust antitumor immunity by CD4+ Th2 cells." (PMID 33652749, 2021). "Further efforts are required to better understand TSLP functions in breast cancer." (PMID 33216733, 2020). "Here, we found that upregulation of TSLP and MIA was associated with better survival outcomes, which contradicts previous studies indicating that these genes interact with other pathways to promote proliferation and growth of breast cancer cells." (PMID 32756008, 2020). "In breast cancer, three studies demonstrated a tumor-promoting role for TSLP." (PMID 33042121, 2020). "Interestingly, here we found that TSLP expression is reduced in breast cancer patients and correlates positively with a favorable prognosis, both in disagreement and agreement with previous reports." (PMID 33216733, 2020). "The first identification of a role for TSLP in cancer was in pancreatic and breast cancers, in which TSLP, secreted by either CAFs or tumor cells, respectively, was found to exert tumor-promoting functions through the establishment of predominant Th2-type inflammation in the tumor microenvironment." (PMID 33042121, 2020). "Indeed, IL-1 was shown to be a key factor for activation of TSLP secretion in both pancreatic and breast cancer, where the use of the IL-1R antagonist anakinra reduced TSLP availability in vitro and in vivo." (PMID 33042121, 2020). "In this study, we reported that arctigenin, a bioactive compound from Arctium lappa L., could decrease tumor-promoting cytokines GM-CSF, MMP-3, MMP-9 and TSLP in breast cancer cells." (PMID 32887217, 2020). "Finally, we sought to investigate the effects of GM-CSF and TSLP on arctigenin-inhibited breast cancer progression in vivo." (PMID 32887217, 2020).